TSC2 (TSC complex subunit 2)
Diseases named in the same sentence as TSC2 in open-access papers (continued):
Sharing a sentence is not in itself a finding about the gene and the disease.
tumor (continued). "However, the gene‐level integrated analysis revealed heterogeneity in expression, copy number variation and methylation status of MDM4, RRAGC, HERC2, BIRC3 and TSC2 genes within and across individual tumours, suggesting that they may not be ideal biomarkers for PDAC." (PMID 35061935, 2022). "The tumor suppressors, TSC1 and TSC2, function in both Drosophila and mammals as negative regulators of Rheb." (PMID 33329069, 2020). "During xenograft studies of Tsc2-null Eker rat ELT3 cells, which have been used extensively as models for TSC and LAM, we identified a rapamycin non-responsive tumor which was used to develop a rapamycin-resistant cell line, termed ELT3-245." (PMID 30816188, 2019). "In contrast, torin did not significantly affect tumor growth, consistent with the lack of effect on TFEB nuclear localization, despite suppressed phosphorylation of classic mTORC1 substrates (p-4E-BP1 and p-p70S6K) in TSC2 KO tumor lysates." (PMID 36357396, 2022).
cancer (164 papers, 2007 to 2026). A tumor composed of atypical neoplastic, often pleomorphic cells that invade other tissues. "Our research has demonstrated that TSC2-deficient cells and various cancer cells exhibit variability in their ferroptosis resistance mechanisms." (PMID 40867343, 2025). "Mutations in the TSC1 and TSC2 genes of these complexes also activate the mTOR pathway and induce cancers." (PMID 37240915, 2023). "Accordingly, one study has evaluated mTOR and Hsp90 inhibitors in combination in TSC1 or TSC2 deficient cancer models." (PMID 35883484, 2022). "Among these, the genes involved in PI3K-Akt-mTOR signaling axis, such as PTEN, NF1 (neurofibromin 1), TSC1(TSC complex subunit 1), TSC2 (TSC complex subunit 2), were associated with inherited risk for both cancer and ASD." (PMID 36339838, 2022). "In this study we searched for cancer cell lines with bi-allelic inactivating mutations in TSC1 or TSC2 from this resource." (PMID 33891611, 2021). "Mutation and loss of function of TSC1 and/or TSC2 also occur in a variety of sporadic cancers, and rapamycin and related drugs show highly variable treatment benefit in patients with such cancers." (PMID 33891611, 2021). "In conclusion, we have identified and validated five cancer cell lines that have complete loss of either TSC1 or TSC2, and consequent constitutive mTORC1 activation." (PMID 33891611, 2021). "In this study, we identified and validated five cancer cell lines with TSC1 or TSC2 mutations and performed a kinase inhibitor drug screen with 197 compounds." (PMID 33891611, 2021). "Future works on the mechanistic basis for CaM-mediated regulation of TSC2 will thus expand our strategies to combat various metabolic diseases and/or cancer progression associated with aberrant mTORC1 signaling." (PMID 34198993, 2021). "Here we sought to identify and characterize cancer cell lines with complete loss of either TSC1 or TSC2, and then to examine their sensitivity to a broad panel of kinase inhibitors, with a goal to identify additional inhibitors beyond rapalogs." (PMID 33891611, 2021). "To find new anti-cancer drug therapies, we wanted to exploit homeostatic vulnerabilities within Tuberous Sclerosis Complex 2 (TSC2)-deficient cells with mechanistic target of rapamycin complex 1 (mTORC1) hyperactivity." (PMID 30308940, 2018). "In this study, we demonstrate that nelfinavir and mefloquine show therapeutic promise as a drug combination that has high potency to kill TSC2-deficient cells and cancer cells with high mTORC1 activity." (PMID 30308940, 2018). "Increased mTORC1 signaling from TSC1/TSC2 inactivation is found in cancer and causes tuberous sclerosis complex (TSC)." (PMID 28695825, 2017). "In agreement, the effects of UII on migration in TSC2-deficient cells required the induction of proliferative and cytokinetic signaling pathways commonly increased in cancer (i.e., Erk MAPK, Fak)." (PMID 27458154, 2016). "Herein, we found that rapamycin treatment promotes TGM2 expression in mTORC1-hyperactive cancer cells, including tsc1-/- and tsc2-/- MEFs, TSC2-deficient patient-derived cells, MCF-7 and 786-O cells." (PMID 26872016, 2016). "Our findings in TSC2-deficient models, which exhibit mTORC1 hyperactivation, suggest that dysregulated iron metabolism and ferroptosis resistance are hallmarks of mTORC1-driven cancers." (PMID 40867343, 2025). "In addition, we previously demonstrated that p16 loss increases mTORC1 activity, and a recent study found that cancers with increased mTORC1, such as those with TSC2 deficiency, are highly sensitive to inhibitors of IMPDH." (PMID 38626341, 2024).
cancer (continued). "The bi-steric mTORC1-selective inhibitor RMC-5552 is now in human clinical trials and, based on the results presented herein, has the potential to benefit patients with TSC syndrome tumors, and patients with the common cancers in which TSC1/TSC2 mutations drive hyperactivated mTORC1 activity." (PMID 37909334, 2023). "In posttherapy HPD tumors, several somatic mutations were observed in known cancer genes that include tumor suppressor genes such as TSC2 and VHL, along with transcriptional upregulation of cancer signaling pathways, which include IGF-1, ERK/MAPK, and PI3K/AKT." (PMID 35399666, 2022). "Inactivating TSC1 and TSC2 mutations also occur rarely in multiple cancer types." (PMID 33891611, 2021). "More rarely TSC1/TSC2 mutations have been identified in many other cancer types, though whether they are important driver events or passenger mutations is not clear in many instances." (PMID 33891611, 2021). "Notably, most of cancer-derived mutations and functionally important residues in TSC2 are enriched on the central core module, supporting the pathological significance of TSC complex in these diseases." (PMID 33436626, 2021). "Omipalisib, or another inhibitor of both major mTORC1 growth pathways and pAkt, might provide therapeutic options for TSC2-deficient cancers including, but not limited to, LAM." (PMID 31878201, 2019). "Thus, our study provides a rationale for using G2/M checkpoint inhibitors such as WEE1 inhibitors to target not only TSC2-deficient cells but cancer cells with hyperactivation of the mTORC1 pathway." (PMID 30266942, 2018). "Considering the ability of an anti-oxidant diet to accelerate the formation of TSC2-deficient tumors in mice, implementation of pro-oxidant diets may have the potential to prevent or delay the development of TSC2-deficient cancer." (PMID 29449538, 2018). "TSC1 or TSC2 dysfunction is also implicated in uncontrolled growth and cancer." (PMID 28632179, 2017). "These TSC1/TSC2 loss of function mutations activate mammalian target of rapamycin (mTOR) protein kinases, which promote both cell proliferation and survival, have been implicated in various types of cancer." (PMID 27377753, 2016). "Indeed, not only does loss of dystrophin affect synaptic transmission and has recently been found to cause susceptibility to malignant tumors in mice, it also affects activity of Akt, a kinase that directly regulates TSC2." (PMID 24204314, 2013). "Our findings highlight a critical role for the DYRK1A/TSC2/mTORC1 signaling pathway in regulating cDC1 functions in antitumor immunity, offering potential strategies to improve cancer immunotherapy." (PMID 42024470, 2026). "Focusing on 14-3-3ζ which was reported to be highly expressed in various cancers, we found that BA also inhibited the binding of 14-3-3ζ to TSC2, Rictor, Raptor, mTOR, FOXO1, FOXO3a, and STAT3." (PMID 40316727, 2025). "Database synthesis corroborated disease associations involving MTOR and its partners (e.g., TSC2, RICTOR, RPTOR, MLST8, AKT1 across selected carcinomas)." (PMID 41300706, 2025). "AP‐1 transcription factor network, with known roles in signalling associated with proliferation, angiogenesis and survival, in various cancers, was also a high‐ranking biological pathway found in TSC2‐ EVs (4.505‐fold enrichment)." (PMID 37337371, 2023).
cancer (continued). "TSC2 downregulation occurs in various cancers such as NSCLC, and low TSC2 expression predicts poor patient prognosis." (PMID 37256211, 2023). "The PI3K/AKT/mTOR pathway is commonly dysregulated in human cancer, due to mutation of dominantly acting oncogenes (PIK3CA, AKT isoforms, MTOR), inactivation of tumor suppressor genes (PTEN, TSC1, TSC2, PIK3R1), and amplification of growth-promoting oncogenes." (PMID 37909334, 2023). "We also identified medically actionable variants in eight other cancer-related SFs genes, including APC, MAX, MSH6, MLH1, PALB2, PMS2, SDHB, and TSC2." (PMID 36143288, 2022). "Among them, ARID1A, TSC2, JAK3, CIC, CINNB1, and SETD2 were mutated at the early stage of carcinogenesis, which played an essential role in advancing early cancer development and progression." (PMID 35795211, 2022). "Promising new splice variants with a potential link with cancer are CSF1, PLOD2, SLK, SPAG9 and TSC2." (PMID 33845831, 2021). "The reason why some patients with TSC1 or TSC2 mutant cancers have dramatic responses to rapalogs while the vast majority do not, is not understood." (PMID 33891611, 2021). "RPTOR, along with TSC2, is a part of the mTOR signaling pathway known to affect many different types of cancer." (PMID 33466343, 2021). "Molecular studies in cancer showed that Wnt signaling controlled the activity of the mTOR pathway via GSK3β phosphorylation of TSC2, promoting the inhibitory function of TSC2 on mTOR activity." (PMID 34358226, 2021). "SGK1, which is activated by 3-phosphoinositide dependent kinase-1 (PDK1), contributes to the maintenance of residual mTORC1 activity and cancer cell growth through direct phosphorylation and inhibition of tuberous sclerosis 2 (TSC2)." (PMID 33542904, 2020). "ERK and RSK have been shown to directly act on TSC2 and mTORC1 phosphorylation, respectively, in other cancer types, and that crosstalk exists between these pathways has been demonstrated." (PMID 30266989, 2019). "A pan-cancer multi-omic integrative study correlated miR-21-3p levels with TSC2 expression, mTOR pathway activation, and a predictive signature for mTOR inhibitor-sensitivity in PPGLs and other cancers." (PMID 31410193, 2019). "Various cancer types have been shown to carry druggable targets for mTOR inhibitors, including mutations in MTOR, TSC1, TSC2, NF1, PI3KCA, PIK3CG, STK11, and RHEB." (PMID 31443247, 2019). "The family history of these patients included BC/OC and other types of cancer, as shown in the pedigrees of 2 patients with PALB2 and TSC2 mutations." (PMID 28423363, 2017). "For example, PIM2 modulates mTORC1 activity through phosphorylation of TSC2 in other cancers, while PIM1 phosphorylates PRAS40 thereby relieving its inhibitory effects on mTORC1 with a subsequent increase in mTORC1 activity." (PMID 27120806, 2016). "First, it is clear that there is a striking correlation between inactivating mutations in TSC1 or TSC2, and activating mutations in MTOR, and response to rapalog therapy in several cancer types." (PMID 26137524, 2015). "The first cancer type in which this was seen was PEComa, a rare sarcoma subtype in which mutations in TSC1 or TSC2 are common." (PMID 26137524, 2015). "Metformin mediates mammalian target of rapamycin (mTOR) pathway via the activation of AMPK and tuberous sclerosis complex 2 (TSC2), phosphorylation of TSC2 which leads to an inhibition of mTOR signaling and reduction in protein synthesis for cancer cells." (PMID 24647047, 2014). "Five of these genes, PTEN, TSC2, RPS6KA3, MYCN and Myo5A, form a connected module (module 9) associated with cancer biology." (PMID 24204314, 2013).
cancer (continued). "This regulatory interaction between TSC2 and N signaling is reminiscent of recent findings in Drosophila sensory organ precursors, mouse embryonic fibroblasts, and mammalian cancer cells." (PMID 23144631, 2012). "Since shRNA will be difficult to use in cancer treatment, it is likely that small molecule inhibitors of TSC2 function will need to be developed for the treatment of Rb mutant cancers." (PMID 20706560, 2010). "We have identified that inactivation of TSC2 in Rb mutant cancer cells will induce a synergistic cell death." (PMID 20706560, 2010). "The TSC2 gene is known to be involved in mammalian cell cycle control and its overexpression is thought to exert an antitumor effect on cancer cells." (PMID 17597835, 2007). "The role of TSC2 and the mTOR signaling pathway in cancer progression is well-established in humans, and the high frequency of these mutations in chimpanzee samples may indicate a parallel, yet distinct, evolutionary adaptation in this species." (PMID 41522204, 2026). "Some studies have demonstrated that in TSC2-mutated cancer both combination therapy with PD-1 and CTLA-4 antibodies, as well as monotherapy, can enhance CD8+ T cell infiltration in TSC2-deficient human tumors, with the level of infiltration correlating with treatment response." (PMID 40994638, 2025). "On the contrary, TSC2 mutations are not very common, with TSC2 loss reported in 0.1% of all cancers and TSC2 point mutations present in 3.39% of tumors." (PMID 38117060, 2024). "The TSC2-SA mutation enhanced both T cell effector function and long-term persistence/memory formation, supporting an approach to engineer better CAR-T cells for treating cancer." (PMID 37788104, 2023). "We evaluated the clinicopathological correlates of the 7 SMGs, together with 6 additional cancer genes identified from at least 2 previous HCC genomics studies and mutated in ≥3 HCCs of the current cohort (APOB, ARID2, CDKN2A, KEAP1, RB1 and TSC2)." (PMID 35508466, 2022). "Interestingly, searching BRSK2 against mTOR yielded several hits describing the involvement of the BRSK2 protein and TSC2 in the regulation of mTOR signaling in different contexts, including cancer cell survival and development." (PMID 36422197, 2022). "In cancer cells harbouring these TSC2 mutations, the TSC2-NTD/TSC2-GAP, or TSC1/TSC2, or TSC2-GAP/Rheb associations may be disrupted, leading to diminished GAP activity toward Rheb and abnormally elevated mTORC1 activity." (PMID 33307091, 2021). "AMPK also phosphorylates TSC complex subunit 2 (TSC2) and regulatory associated protein of MTOR complex 1 (Raptor) and thereby inactivates mTORC1, which in turn elevates cellular autophagy activity and inhibits cancer initiation." (PMID 32807225, 2020). "From variant analysis of 46 cancer susceptibility genes, we identified 7 pathogenic and likely pathogenic germline variants in 7 genes in 7 (8%) of the 87 patients, namely, MUTYH, RET, TSC2, BRCA1, BRCA2, ERCC2 and HRAS." (PMID 29684080, 2018). "This work underpins a critical vulnerability with cancer cells with aberrant signaling through the TSC2-mTORC1 pathway that lack flexibility in homeostatic pathways, which could be exploited with combined nelfinavir and mefloquine treatment." (PMID 30308940, 2018). "However, use of mTORC1 inhibitor in human cancers showed modest efficacy plausibly due to release of the feedback inhibition of the PI 3 kinase/Akt pathway similar to that found in Tsc2 null cells." (PMID 29491408, 2018). "In cancer cells, knockdown of Rb and TSC2 induced synergistic cell death." (PMID 28076433, 2017). "Activated AMPK could phosphorylate tumor suppressor tuberous sclerosis complex 2 (TSC2) to inhibit mTOR activity, which plays a critical role in cancer progression." (PMID 28271076, 2017). "Indeed, Redd1 can inhibit mTOR activity through activation of TSC2, suggesting a possible role for Redd1 in metformin anti-cancer effects in human GB cells." (PMID 25867026, 2015).